ARMC2 (armadillo repeat containing 2)
Description:
Required for sperm flagellum axoneme organization and function (By similarity). Involved in axonemal central pair complex assembly and/or stability (By similarity).
Synonyms: DKFZp434P0714; bA787I22.1; SPGF38
Tractability: No criterion of Open Targets' tractability assessment is met for any kind of drug.
Gene: Protein-coding gene on chromosome 6 (108,848,416 to 108,974,551, forward strand). Ensembl gene ENSG00000118690.
Subcellular location (Human Protein Atlas): Nucleoplasm
Gene Ontology:
Molecular function: protein binding
Biological process: sperm axoneme assembly; cilium organization
Genetic constraint (gnomAD): Loss-of-function variants: 59 observed, 78.29 expected, observed/expected ratio (o/e) 0.75, 90% interval 0.61 to 0.94. The upper end of that interval is the gene's LOEUF score, 0.94, which puts it in group 3 of 6, group 1 being the genes least tolerant of losing a copy. Missense variants: 850 observed, 986.49 expected, observed/expected ratio (o/e) 0.86, 90% interval 0.81 to 0.91. Synonymous variants: 364 observed, 377.76 expected, observed/expected ratio (o/e) 0.96, 90% interval 0.88 to 1.05.
Homologues: Orthologues: chimpanzee ARMC2 (99% identical), macaque ARMC2 (97% identical), dog ARMC2 (85% identical), pig ARMC2 (84% identical), guinea pig ARMC2 (79% identical), rabbit ARMC2 (79% identical), rat Armc2 (73% identical), mouse Armc2 (73% identical), tropical clawed frog armc2 (50% identical), zebrafish armc2 (42% identical), Drosophila melanogaster CG32668 (25% identical).
Diseases named in the same sentence as ARMC2 in open-access papers:
ARMC2 is named in the same sentence as 5 diseases in open-access papers, as found by Europe PMC text mining. Sharing a sentence is not in itself a finding about the gene and the disease. The quoted sentences say what the papers report.
male infertility (3 papers, 2020 to 2022). The inability of the male to effect fertilization of an ovum after a specified period of unprotected intercourse. "In human patients, Armc2 defects have been linked only to male infertility, suggesting that Armc2 is expendable for the assembly of motile cilia in the airways and ventricular system." (PMID 34982025, 2022). "ARMC2 was found to be involved in male infertility caused by the multiple morphological abnormalities of the sperm flagella (MMAF)." (PMID 35685372, 2022). "The mammalian homologue of ARMC2 has been linked to reduced lung function and male infertility but the precise role of ARMC2 in the assembly of motile cilia remained unknown." (PMID 34982025, 2022). "Mutations in mammalian Armc2 cause sperm malformations resulting in male infertility." (PMID 34982025, 2022). "Here, we show that IFT of radial spokes in Chlamydomonas requires ARMC2/PF27, a conserved armadillo repeat protein associated with male infertility and reduced lung function." (PMID 34982025, 2022). "Mutations in ARMC2 (armadillo repeat containing 2), CFAP43 and CFAP44 cause male infertility associated with sperm axonemal central pair defects." (PMID 31781811, 2020).
chronic obstructive pulmonary disease (1 paper, 2021). A chronic and progressive lung disorder characterized by the loss of elasticity of the bronchial tree and the air sacs, destruction of the air sacs wall, thickening of the bronchial wall, and mucous accumulation in the bronchial tree. "A genome-wide association and large-scale follow-up study revealed an association for ARMC2 with pulmonary function and chronic obstructive pulmonary disease (COPD)." (PMID 34912852, 2021).
teratozoospermia (1 paper, 2022). "Several teratozoospermia-associated gene mutations, including F-box only protein 43 (FBXO43), armadillo repeat-containing protein 2 (ARMC2), SEPTIN12, and AGBL carboxypeptidase 5 (AGBL5), have been identified by measuring exonic mutations in blood samples using whole exome sequencing technology." (PMID 36292606, 2022).
genetic disease (1 paper, 2022). "The paralogs of ARMC3 are involved in causing various genetic disease conditions in humans, e.g., ARMC2 (OMIM: 618424; 6q21) variants cause severe asthenoteratozoospermia in humans and mice." (PMID 36553564, 2022).
ARMC2 also shares sentences with these, for which no sentence is quoted: primary ciliary dyskinesia (1 paper).